FUT2 (fucosyltransferase 2 (H blood group))
Description:
Catalyzes the transfer of L-fucose, from a guanosine diphosphate-beta-L-fucose, to the terminal galactose on both O- and N-linked glycans chains of cell surface glycoproteins and glycolipids and the resulting epitope regulates several processes such as cell-cell interaction including host-microbe interaction, cell surface expression and cell proliferation. Preferentially fucosylates gangliosides GA1 and GM1 in the antrum, cecum and colon and in the female reproductive organs (By similarity). Fucosylated host glycoproteins or glycolipids mediate interaction with intestinal microbiota influencing its composition. Creates a soluble precursor oligosaccharide FuC-alpha ((1,2)Galbeta-) called the H antigen which is an essential substrate for the final step in the soluble ABO blood group antigen synthesis pathway.
Synonyms: Se; SEC2; sej; Se2; B12QTL1
Tractability: Antibody: UniProt predicts a signal peptide or a membrane-spanning region.
Target class: Enzyme; Transferase
Safety:
Unwanted effects reported when the protein is acted on. In parentheses: how it was acted on, where the effect was seen, and who reports it.
alcoholism (source: ClinPGx)
Gene: Protein-coding gene on chromosome 19 (48,695,957 to 48,705,951, forward strand). Ensembl gene ENSG00000176920.
Subcellular location: Golgi apparatus, Golgi stack membrane
Subcellular location (Human Protein Atlas): Plasma membrane; Cytosol
Pathways (Reactome):
Metabolism: ABO blood group biosynthesis; Glycosphingolipid biosynthesis; Lewis blood group biosynthesis
Gene Ontology:
Molecular function: galactoside 2-alpha-L-fucosyltransferase activity; protein binding; alpha-(1,2)-fucosyltransferase activity; fucosyltransferase activity
Biological process: carbohydrate metabolic process; glycoprotein biosynthetic process; glycosphingolipid biosynthetic process; L-fucose catabolic process; oligosaccharide biosynthetic process; protein O-linked glycosylation via fucose; carbohydrate derivative biosynthetic process
Cellular component: extracellular exosome; Golgi apparatus; Golgi membrane; Golgi cisterna membrane; membrane
Genetic constraint (gnomAD): Loss-of-function variants: 4 observed, 4.86 expected, observed/expected ratio (o/e) 0.82, 90% interval 0.4 to 1.71. That is too few expected variants to judge how well the gene tolerates losing a copy. Missense variants: 419 observed, 483.25 expected, observed/expected ratio (o/e) 0.87, 90% interval 0.8 to 0.94. Synonymous variants: 182 observed, 199.65 expected, observed/expected ratio (o/e) 0.91, 90% interval 0.81 to 1.03.
Homologues: Orthologues: chimpanzee FUT2 (99% identical), macaque FUT2 (94% identical), dog FUT2 (84% identical), pig FUT2 (83% identical), rabbit FUT2 (77% identical), guinea pig FUT2 (70% identical), tropical clawed frog fut2 (54% identical), tropical clawed frog fut1 (53% identical), Caenorhabditis elegans B0205.4 (23% identical). Paralogues in human: FUT1 (59% identical).
Diseases named in the same sentence as FUT2 in open-access papers:
FUT2 is named in the same sentence as 137 diseases in open-access papers, as found by Europe PMC text mining. Sharing a sentence is not in itself a finding about the gene and the disease. The quoted sentences say what the papers report.
Crohn disease (30 papers, 2011 to 2024). A gastrointestinal disorder characterized by chronic inflammation involving all layers of the intestinal wall, noncaseating granulomas affecting the intestinal wall and regional lymph nodes, and transmural fibrosis. "The genetic polymorphisms of Fucosyltransferase 2 (FUT2) have also been associated with Crohn’s diseases in multiple independent genome-wide association studies from distinctive populations." (PMID 33293650, 2020). "Genome-wide association studies show that FUT2 nonsense polymorphisms are associated with increased risk for Crohn’s disease and primary sclerosing cholangitis." (PMID 31329635, 2019). "The Fut2 has been identified as a risk factor in Crohn’s disease, a chronic gastrointestinal inflammatory disease that is characterised by abnormal function of the immune system." (PMID 30181591, 2018). "Although the role of fucose on ECs in intestinal inflammation is not clearly understood, recent genome-wide association studies have implicated Fut2 in the pathogenesis of many intestinal inflammatory diseases including Crohn’s disease in the human population." (PMID 26522513, 2015). "The role of FUT2 in gut microbial ecology is further substantiated by the association of its SNP rs281379 (r2 = 0.76 with rs492602) with Crohn's disease (CD), as found in a sample of over 50 K individuals." (PMID 24586186, 2014). "Fine-mapping of the first locus pinpointed the FUT2 gene, which encodes a fucosyltransferase enzyme and has previously been associated with Crohn's disease." (PMID 24586186, 2014). "We found urine fucose concentration to be associated with variants in the FUT2 gene, which is linked to gut microbial ecology in general, and to Crohn's disease in particular." (PMID 24586186, 2014). "Unlike many of the gene variants examined in GWAS, the polymorphism in the fucosyl transferase gene FUT2 linked to Crohn’s disease leads to a coding change with a clear effect." (PMID 21994779, 2011). "Another notable results from the MSEA found microbes with differential abundance in Crohn’s disease are enriched for microbes associated with ATG16L1, CCL11 and FUT2, all of which have been implicated in the pathology of Crohn’s diseases, an inflammatory bowel disease (IBD)." (PMID 33293650, 2020). "Additionally, ABO and FUT2 variants are risk factors for a number of different diseases, including Crohn’s disease, AIDs, Type 1 diabetes, and infectious diseases." (PMID 27871240, 2016). "Thus, this variant of FUT2 links differential susceptibility to viral infection with risk of developing Crohn’s disease." (PMID 21994779, 2011). "The FUT2 gene, encoding for fucosyltransferase 2, a protein present at the Golgi membrane that is associated with regulating the composition and function of secreted glycans in mucosal tissues of the gut and other tissues, being a predisposing factor for Crohn’s disease is an example." (PMID 36558520, 2022). "Interestingly, genome-wide association studies have revealed a common risk factor for PSC and Crohn’s disease in the fucosyltransferase 2 (FUT2) locus, which influences fecal and bile bacterial composition and has recently been linked to the development of hepatobiliary abnormalities in mice." (PMID 32192118, 2020). "The association of fucosyltransferase 2 (FUT2) gene polymorphisms with PSC, Crohn’s disease, and biochemical features of cholestasis has been found." (PMID 36771465, 2023). "This suggests that the non-target metabolite m/z 363.0888 has immunomodulatory capabilities through FUT2 and thus has potential effects in Celiac, Crohn’s disease, and type 1 diabetes." (PMID 34229738, 2021). "A recent report links a dysfunctional fucusyltransferase-2 (FUT2) to PSC and Crohn disease (CD), and the FUT2 genotype to the altered composition of the microbiota in the intestine and bile." (PMID 27834858, 2016). "For example, the intestinal microbiome was found to vary by both Crohn’s disease status and FUT2 genotype." (PMID 27871240, 2016).
Crohn disease (continued). "Several studies have revealed that defects in epithelial FUT2 predispose individuals to several diseases, including inflammatory bowel disease (IBD, especially Crohn’s disease), acute and chronic inflammatory disorders such as type I diabetes, and chronic pancreatitis." (PMID 36973740, 2023). "Specifically, although not included in the top genes, FUT2 for Bifidobacterium was suggested to be the causal gene for Crohn's disease (CD) in previous study." (PMID 34922623, 2021). "GWAS identified a FUT2 variant (AA genotype) associated with an altered gut microbiome, FUT2 nonsecretor-status and increased risk of Crohn's disease." (PMID 30356925, 2018). "The non-secretor phenotype or the FUT2 genotype AA has been associated with several diseases, for example with an increased risk for Crohn's disease, type 1 diabetes, experimental vaginal candidiasis, and urinary tract infections." (PMID 24733310, 2014). "It has been newly reported that fucosyltransferase 2 (Fut2) non-secretor of state (individuals lacking a functional copy of Fut2 are known as non-secretors) is associated with Crohn's Disease (CD) susceptibility, however the mechanism remains unknown." (PMID 33722220, 2021). "Moreover, variants in both FUT2 and FUT3 have been shown in GWAS to increase susceptibility to diseases associated with both mucosal surface pathobiology and microbiome composition, such as cystic fibrosis, Crohn’s disease, and ulcerative colitis." (PMID 28143570, 2017). "One of the B12-associated loci, FUT2, has previously been associated with reduction in liver enzymes including alkaline phosphatase (ALP) and cholesterol levels, increased risk of Crohn's disease, psoriasis, retinal vascular caliber and type 1 diabetes and protection against Norovirus infection." (PMID 23754956, 2013). "Although one study involving 1503 individuals failed to confirm the association of gut microbiome composition with ABO or secretor status, the influence of FUT2 genotype on the gut microbiota has been highlighted not only in healthy individuals but also in patients with Crohn's disease." (PMID 28167958, 2017).
inflammatory bowel disease (18 papers, 2014 to 2025). A spectrum of small and large bowel inflammatory diseases of unknown etiology. "Loss-of-function mutations in FUT2 result in an altered gut microbiome, contributing to the development of inflammatory bowel diseases." (PMID 38840912, 2024). "FUT2 encodes a Golgi stack membrane protein and is highly associated with the development of inflammatory bowel disease." (PMID 31595719, 2019). "Significantly, functional FUT2 enables the secretion of histo-blood group antigens (HBGAs) in gastrointestinal mucosa by modifying the H antigens, and the mutation of FUT2 (non-secretors) gives rise to susceptibility to diseases such as enteric pathogen infections and inflammatory bowel disease." (PMID 40821120, 2025). "Previous studies have reported FUT2 activity to be associated with inflammatory bowel disease (IBD) and Campylobacter infection, and secretors from Bangladesh have been reported to be less likely to have symptomatic enteric infections by certain ETEC strains." (PMID 40431244, 2025). "The FUT2 loss-of-function mutations are very common and related with inflammatory bowel disease (IBD)." (PMID 36699724, 2022). "Several autoimmune diseases such as the inflammatory bowel disease (IBD), and type I diabetes have been associated with the FUT2 polymorphism." (PMID 24733310, 2014). "Similarly, fucosyltransferase 2 (FUT2) and serum vimentin (VIM) have been implicated in other chronic inflammatory conditions, such as inflammatory bowel disease, but their roles in AD remain uncharacterized." (PMID 41583462, 2025). "Like inflammatory bowel disease, the SNP of FUT2 was correlated to CRC." (PMID 40821120, 2025). "To date, many studies have demonstrated that the interaction of HBGA with the host microbiota is the cause of pathogenesis of intestinal diseases, making FUT2 non-secretor a risk factor for inflammatory bowel disease (IBD) due to the lack of HBGA." (PMID 35923409, 2022). "One network cluster associates with the FUT2 gene, which is a susceptibility gene for CD that contributes to the composition of the gut microbial community even in individuals without inflammatory bowel disease." (PMID 25853426, 2015).
breast carcinoma (15 papers, 2016 to 2024). "For example, a previous study demonstrated that Fut2 plays important roles in promoting the growth, adhesion, and migration of breast cancer cells." (PMID 36739428, 2023). "Nevertheless, FUT2 overexpression increased cell migration and invasion in vitro and metastasis of breast cancer in vivo." (PMID 36973740, 2023). "This is in contrast to results in breast cancer cell lines and lung adenocarcinoma cells, where FUT2 enhances cell migration and invasion." (PMID 36973740, 2023). "B3GALT5 and FUT1/FUT2 have been known to be involved in the biosynthesis of Globo H in breast carcinoma cell lines." (PMID 32237061, 2020). "Inhibition of cancer cell progression, angiogenesis and metastasis by FUT1 or FUT2 knockdown reduced expression of alpha 1, 2-fucosyl glycans has been found in many cancers including breast cancer." (PMID 30854233, 2019). "Glycan products of FUT1 and FUT2, such as Globo H and Lewis Y, are highly expressed on malignant tissues, including breast cancer." (PMID 30854233, 2019). "We have demonstrated the important roles of FUT1 and FUT2 in breast cancer as evidenced by their regulation of cell morphology, proliferation, adhesion, migration, and mammosphere formation in vitro and tumorigenicity and metastasis in vivo." (PMID 30854233, 2019). "Here, we investigated the impacts of alpha 1, 2-linked fucose on breast cancer biology and CSC properties using lentiviral system to knockdown and electroporation to overexpress FUT1 and FUT2.." (PMID 30854233, 2019). "FUT2 also plays a role in cell proliferation, and its knockdown inhibited cell proliferation in bovine venular endothelial cells, malignant human A431 cells, and breast cancer cells." (PMID 37686244, 2023). "However, other researchers found that silencing Fut2 suppressed cell migration, whereas Fut2 overexpression increased cell migration, invasion and metastasis in breast cancer." (PMID 36739428, 2023). "The effect of FUT2 on tumor development and progression was also observed in breast cancer." (PMID 35899200, 2022). "However, the roles of FUT1 and FUT2 in cancer stem cells (CSCs) and tumorigenicity of breast cancer have yet to be delineated." (PMID 30854233, 2019). "Herein, we investigated the roles of FUT1 and FUT2 in breast cancer." (PMID 30854233, 2019). "For example, FUT1 and FUT2 promote growth, adhesion, migration, and cancer stem cell (CSC) properties of breast cancer." (PMID 34745942, 2021). "Thus FUT1 and FUT2 may serve as good drug targets for breast cancer therapy." (PMID 30854233, 2019). "In breast cancer, FUT1 and FUT2 have been involved in regulating growth, adhesion, and migration of breast cancer and might serve as a therapeutic target." (PMID 38670309, 2024). "Overexpression of FUT1 or FUT2 promotes the migration and invasion of tumor cells in breast cancer cell lines and metastasis in vivo, whereas FUT1 or FUT2 knockdown reduces Globo H and decreases mesenchymal-like markers, such as fibronectin, vimentin, and twist." (PMID 34948129, 2021). "Silencing of FUT1 or FUT2 suppressed cell migration in wound healing assay, whereas FUT1 and FUT2 overexpression increased cell migration and invasion in vitro and metastasis of breast cancer in vivo." (PMID 30854233, 2019). "In addition, FUT1 and FUT2 are capable of generating FGM1 and Globo H in small cell lung cancer cells and breast cancer cells, respectively." (PMID 30854233, 2019). "Furthermore, to determine whether FUT1 and FUT2 promote breast cancer metastasis in vivo, MDA-MB-231 stably and constitutively expressing luciferase by lentiviral-mediated gene transfer was transfected with empty vector, Flag-FUT1 or Flag-FUT2." (PMID 30854233, 2019). "In addition, in silico analyses showed that the mRNA levels of fucosyltransferase genes FUT2, FUT3, and FUT7 also upregulated in breast cancer tissues compared with the adjacent noncancerous breast tissues in 113 pairs of breast cancer from the TCGA database." (PMID 33976130, 2021).
colitis (13 papers, 2016 to 2024). Inflammation of the colon. "Defective Fut2 was demonstrated to be associated with several kinds of intestinal diseases, especially colitis." (PMID 38550777, 2024). "Our previous study revealed that IEC-specific deficiency of Fut2 aggravates colitis and disturbs the gut microbe and metabolism." (PMID 38550777, 2024). "Our previous study reported that intestinal epithelium‐specific Fut2 deficiency exacerbates dextran sulfate sodium (DSS)‐induced colitis." (PMID 36739428, 2023). "Our previous study showed that fucosyltransferase 2 (Fut2) deficiency is closely related to colitis." (PMID 36739428, 2023). "Collectively, our data revealed that intestinal epithelium-specific Fut2 deficiency mice were susceptible to colitis through modulation of gut microbiota and generation of LPC." (PMID 33722220, 2021). "Briefly, Fut2 deficiency in intestinal epithelium aggravates the intestinal barrier injury in DSS-induced colitis." (PMID 33722220, 2021). "Collectively, these results demonstrated that Fut2 deficiency increased inflammatory response in DSS induced acute colitis." (PMID 33722220, 2021). "Moreover, we demonstrated that Fut2 deficiency in intestinal epithelium exacerbated colitis, including promoting release of pro-inflammatory cytokines and aggravating epithelial barrier damage." (PMID 33722220, 2021). "Collectively, intestinal epithelium-specific loss of Fut2 exacerbates DSS-induced colitis." (PMID 33722220, 2021). "Fucosylation has been established as a crucial modification for maintaining normal colon homeostasis, and previous studies have highlighted the protective effects of fucose supplementation through FUT2-mediated fucosylation against colitis onset." (PMID 38979515, 2024). "The observed upregulation of Reg3g and Fut2 by DKT in the colonic epithelial cells prompted us to interrogate the involvement of IL-22 in DKT-mediated amelioration of colitis." (PMID 35720414, 2022). "To evaluate the role of Fut2 in colitis, we induced colitis in both WT and Fut2△IEC mice by administering 3% DSS in drinking water for 7 days." (PMID 33722220, 2021). "The role of Fut2 in IBD susceptibility was to modulate gut microbiota structurally and functionally, thus altering generation of LPC which was proved to exacerbate colitis." (PMID 33722220, 2021). "It has been proposed that fucosylation deficiency leads to colitis and adenocarcinoma in mice, while it remains unclear whether α-1,2 fucosylation (FUT1, FUT2) is relevant to colorectal cancer." (PMID 36973740, 2023). "In UC patients, the mutant alleles and genotypes of FUT2 (C357T, A385T, and G428A) did not statistically differ between patients with extensive colitis and distal colitis." (PMID 28167958, 2017). "Mutant alleles of FUT2 (C357T, A385T, and G428A) were not significantly different either between the distal colitis group and the extensive colitis group (P > 0.05)." (PMID 28167958, 2017). "Interestingly, the R. gnavus fucosidase ATCC_03833 applied in our study mainly cleaves α1,2-linked fucose, the product of the FUT2 enzyme, yet we did not observe any effect of increased fucosidase activity on the severity of colitis in treated mice." (PMID 36567940, 2022). "The data above demonstrated that the expression of Fut2 and α-1,2-fucosylation decreased in IBD patients and experimental colitis." (PMID 33722220, 2021). "Based on the decreased expression level of Fut2 and α-1,2-fucosylation in IBD, we hypothesized a crucial functional relevance of Fut2 in colitis." (PMID 33722220, 2021).